CFAP95 (cilia and flagella associated protein 95)
Description:
Microtubule inner protein (MIP) part of the dynein-decorated doublet microtubules (DMTs) in cilia axoneme, which is required for motile cilia beating.
Synonyms: C9orf135
Tractability: Small molecule: a structure with a bound ligand is known. Antibody: UniProt places it where antibodies can reach, with high confidence; its Gene Ontology location is reachable by antibodies, with high confidence; UniProt predicts a signal peptide or a membrane-spanning region. PROTAC: ubiquitination databases record sites on it.
Gene: Protein-coding gene on chromosome 9 (69,820,815 to 69,906,655, forward strand). Ensembl gene ENSG00000204711.
Subcellular location: Cytoplasm, cytoskeleton, cilium axoneme; Cytoplasm, cytoskeleton, flagellum axoneme; Cell membrane; Cytoplasm
Subcellular location (Human Protein Atlas): Mid piece; Principal piece
Gene Ontology:
Biological process: flagellated sperm motility
Cellular component: axonemal microtubule; cytoplasm; plasma membrane; axonemal A tubule inner sheath; sperm flagellum; axoneme
Genetic constraint (gnomAD): Loss-of-function variants: 11 observed, 14.44 expected, observed/expected ratio (o/e) 0.76, 90% interval 0.48 to 1.26. The upper end of that interval is the gene's LOEUF score, 1.26, which puts it in group 5 of 6, group 1 being the genes least tolerant of losing a copy. Missense variants: 200 observed, 193.4 expected, observed/expected ratio (o/e) 1.03, 90% interval 0.92 to 1.16. Synonymous variants: 64 observed, 71.44 expected, observed/expected ratio (o/e) 0.9, 90% interval 0.73 to 1.1.
Homologues: Orthologues: chimpanzee CFAP95 (97% identical), macaque CFAP95 (93% identical), guinea pig CFAP95 (78% identical), rabbit CFAP95 (77% identical), pig CFAP95 (76% identical), dog CFAP95 (76% identical), mouse Cfap95 (62% identical), rat Cfap95 (53% identical), tropical clawed frog CFAP95 (34% identical).
Diseases named in the same sentence as CFAP95 in open-access papers:
CFAP95 is named in the same sentence as 3 diseases in open-access papers, as found by Europe PMC text mining. Sharing a sentence is not in itself a finding about the gene and the disease.
CFAP95 shares sentences with these, for which no sentence is quoted: cancer (1 paper); fibrosarcoma (1); tumor (1).